TBK1 (TANK binding kinase 1)
Diseases named in the same sentence as TBK1 in open-access papers (continued):
Sharing a sentence is not in itself a finding about the gene and the disease.
Obesity (continued). "Since TBK1 and IKKε are activated by obesity-related inflammation and BJ directly inhibits IKKε and TBK1, the reduction in inflammation observed after BJ treatment in this study may be partiallyly and indirectly related due to the indirect effect of improving to the alleviation of metabolic disease." (PMID 35962183, 2022). "Thus, TBK1 and IKKε appear to co-opt insulin targets to conserve energy during obesity." (PMID 24368730, 2013). "In obesity, this AMPK/TBK1 axis was disrupted due to chronically elevated basal TBK1, thereby restricting energy expenditure during fasting." (PMID 42100877, 2026). "In obesity and T2DM, TBK1 mainly plays a key role in regulating metabolic inflammation associated with glucose metabolism." (PMID 40076567, 2025). "Inhibition of TBK1 with ALX in HFD mice reduced IL-17-induced adipose tissue inflammation and improved diet-induced obesity, fatty liver, glucose, and lipid metabolism in mice." (PMID 40076567, 2025). "Moreover, amlexanox, a specific inhibitor of TBK1/IKKɛ, has been shown in other trials to be a prospective medicine of choice for the treatment of inflammation-related illnesses such as liver fibrosis and damage, type 2 diabetes, and obesity-related metabolic dysfunction." (PMID 38302598, 2024). "Amlexanox, a dual inhibitor of TBK1 and IKKε, downstream kinases in the STING pathway, has shown potential in animal models of obesity and type 2 diabetes." (PMID 39669992, 2024). "Under normal conditions, TBK1 phosphorylates the inhibitory site of AMPK18 limiting energy expenditure, which becomes counterproductive during aging and obesity." (PMID 36828933, 2023). "Recent studies have shown that ALX, as a specific inhibitor of TANK-binding kinase 1(TBK1)/IkB kinase ε (IKKε), can suppress chronic inflammation in type II diabetes, non-alcoholic fatty liver, and obesity-related metabolic dysfunction." (PMID 30823934, 2019). "TBK1 can reduce the thermogenesis and catabolism of the mitochondria by inhibiting the activity of AMPK, resulting in energy storage and ultimately leading to obesity." (PMID 38436022, 2024). "Inhibiting IKK by inhibiting TBK1 and increasing AMPK induction can reduce inflammation and increase energy metabolism, which may improve obesity." (PMID 38312740, 2024). "Recently, studies have shown that propolis polyphenols may play an anti-obesity role with the Nrf2 pathway, I-kappa-B kinase epsilon (IKK ε) and TANK binding kinase 1 (TBK1)." (PMID 37063322, 2023). "The co-crystal berberine-ibuprofen is an effective agent for treating obesity through a reduction of the activity of the non-canonical I κB kinases, IKKε and TBK1." (PMID 35962183, 2022). "Both the expression and activity of the non-canonical IKK family member TBK1 are induced in adipose tissues during diet-induced obesity." (PMID 33193441, 2020). "Insights into the critical roles of the noncanonical IKKs in the pathogenesis of obesity and insulin resistance led to a screen of chemical inhibitors, identifying amlexanox as an inhibitor for both TBK1 and IKKε." (PMID 33193441, 2020). "Obesity produces a chronic inflammatory state involving the NFκB pathway, resulting in persistent elevation of the noncanonical IκB kinases IKKε and TBK1." (PMID 24368730, 2013). "We demonstrate here a novel link between obesity and reduced sympathetic activity and β-adrenergic sensitivity, through the inflammation-dependent induction of the noncanonical IκB kinases IKKε and TBK1." (PMID 24368730, 2013). "This creates a negative feedback loop whereby AMPK activates TBK1, which downregulates AMPK, possibly explaining diminished obesity in TBK1 KO mice." (PMID 38660307, 2024). "However, our results suggested that inhibiting TBK1, whether using siRNA or AMX, could not improve hyperglycemia or obesity in db/db mice, a type of mutant mouse of the Lepr gene." (PMID 39030571, 2024).
breast carcinoma (45 papers, 2014 to 2025). "STING or TBK1 inhibition markedly attenuated the MARCH1 deficiency induced by faster proliferation of breast cancer cells." (PMID 39061024, 2024). "TBK1 has been implicated in the facilitation of survival pathways in lung cancer, as well as the promotion of growth in specific subtypes of breast cancer." (PMID 38567349, 2024). "Disruption of STING trafficking, regulated by the Rab7 and TBK1 axis, in breast cancer cells with PTEN loss also supports the role of PTEN on tumour immunogenicity through the cGAS-STING pathway." (PMID 38214828, 2024). "Notably, TBK1’s involvement in survival pathways has been implicated in lung cancer and specific subtypes of breast cancer, underscoring its relevance in the context of tumorigenesis and tumor progression." (PMID 38567349, 2024). "In the case of the lung, another frequent metastatic site, several mechanisms have been implicated; Tank-binding kinase-1 (TBK1)-dependent promotion of proliferation of dormant breast cancer cells and upregulation of periostin (POSTN) expression, leading to Wnt signaling." (PMID 34064392, 2021). "Importantly, the TBK1 K154R mutation obviously promoted the proliferation of breast cancer cells." (PMID 39061024, 2024). "In breast cancer, TANK-binding kinase 1 (TBK1) has been identified as a mediator of platelet-induced EMT." (PMID 39934930, 2025). "Specifically, in Luminal breast cancer hyperactivation of AKT kinase inhibits the formation of the STING-IRF3 complex by binding to TBK1, blocking IFN-I secretion and impairing immune surveillance." (PMID 40567603, 2025). "TBK1 is involved in malignant cell growth in different cancer types, including non-small cell lung cancer, breast cancer, and pancreatic ductal adenocarcinoma 8-11." (PMID 39744441, 2025). "Mechanistically, hyperactivated AKT1 blocked the formation of STING/TBK1/IRF3 trimer in endocrine‐resistant breast cancer." (PMID 39023171, 2024). "Our method for identifying small molecule inhibitors can be used to make fundamental advances in drug design methods for the TBK1 protein which will further help to reduce breast cancer incidence." (PMID 38567349, 2024). "Subsequently, the ubiquitinated TBK1 decreases its interaction with mTOR and attenuates mTOR signaling pathway, thus inhibiting the proliferation of breast cancer cells." (PMID 39061024, 2024). "By finding new TBK1 inhibitors, we hope to make it possible for more targeted and effective breast cancer treatments, which will eventually lead to better patient outcomes and quality of life." (PMID 38567349, 2024). "TBK1-related signaling plays important role in tumor progression, and there is need to work on new methods and workflows to identify new molecules for potential treatments for TBK1-affecting oncologies such as breast cancer." (PMID 38567349, 2024). "In summary, our study confirms that hyperactivated AKT1 in endocrine‐resistant breast cancer can interact with TBK1 to block the activation of cGAS‐STING signaling." (PMID 39023171, 2024). "Our results show that the TBK1‐dependent activation of IRF3 is blunted in endocrine‐resistant breast cancer cells, thereby resulting in the suppression of cGAS‐STING signaling to mediate the endocrine resistance." (PMID 39023171, 2024). "Improving the therapeutic efficacy of Attilizumab in breast cancer by activating the interferon gene STING upstream of TBK1 appeared to provide strong evidence for this conclusion." (PMID 39161768, 2024). "Previous studies have confirmed the distinct role of TBK1 in certain types of cancers, including pancreatic cancer, hepatocellular carcinoma, and breast carcinoma." (PMID 36928362, 2023). "TTK and TBK1 are significantly overexpressed in NHW women with basal breast cancers, and TTK in basal and Luminal A breast cancers from H/L women." (PMID 36494865, 2022).
breast carcinoma (continued). "The most common breast cancer subtype is Luminal A; NHB women with Luminal A breast cancers significantly overexpress PLK1, AURKB, and NDC80, while TBK1 is significantly overexpressed in Luminal A breast cancers from NHW women." (PMID 36494865, 2022). "TBK1 mRNA is significantly overexpressed in Luminal B breast cancers and significantly underexpressed in basal breast cancers." (PMID 36494865, 2022). "In lung and breast cancer cell lines, TBK1 phosphorylates Cdc20 on Ser134 and Cdh1 on Thr20, Ser39, Ser42, Ser58, Ser131, and Ser151." (PMID 35395857, 2022). "Higher TBK1 expression was found in the subtype of breast cancer, cervical cancer, colorectal cancer, gastric cancer, head and neck cancer, kidney cancer, leukemia, liver cancer, and pancreatic cancer compared with that measured in normal tissues or cells." (PMID 33679751, 2021). "In breast cancer, activated TBK1 increased the expression of pro-inflammatory chemokines and infiltration of cytotoxic T cells." (PMID 34903812, 2021). "A latest report denoted that tumor necrosis factor receptor-associated factor (TRAF) family member-associated NF-κB activator (TANK)-binding kinase 1 (TBK1) acted as a mediator of platelet-induced NF-κB activation and EMT in mammary carcinoma cells." (PMID 34722319, 2021). "While the role of TBK1 in breast cancer is controversial, IKKε is an established breast cancer oncogene, overexpressed in 30% of breast cancer cases." (PMID 31930708, 2020). "In breast cancer, TBK1 has been shown to phosphorylate the estrogen receptor (Ser305) to promote its activity and drive resistance to the ER antagonist tamoxifen." (PMID 30223576, 2018). "shRNA kinome screening identified TBK1 as a therapeutic target for human epidermal growth factor receptor 2 (HER2)-positive breast cancer." (PMID 30223576, 2018). "Tank-binding kinase-1 (TBK1), also a reported target of miR-200c, inhibits radiation-induced apoptosis in breast cancer and NSCLC cells." (PMID 29029445, 2017). "MiR-200c overexpression can increase radiosensitivity of human breast cancer cells by targeting TANK-binding kinase 1 (TBK1)." (PMID 28038467, 2017). "Moreover, TBK1 K154R overexpression also promoted faster proliferation in breast cancer cells, which further confirmed the important role of TBK1 K154." (PMID 39061024, 2024). "Because the expression of TBK1 is consistent with that of ERα, TBK1 may become an important prognostic marker of breast cancer subtypes." (PMID 36988258, 2023). "In breast cancer, TBK1 is overexpressed in estrogen receptor α (ERα)‐positive breast cancer." (PMID 36988258, 2023). "However, it was also reported that TBK1 inhibits EMT in breast cancer cells via increasing the expression of estrogen receptors." (PMID 36009179, 2022). "Since the cell cycle is one of the most commonly deregulated cellular processes in cancer, we propose that the mitotic kinases TTK (or Mps1), TBK1, and Nek2 could be novel targets to prevent breast cancer progression among NHBs and H/Ls." (PMID 36494865, 2022). "In breast cancers, TBK1 expression was significantly higher in most breast tumor tissues compared to matched adjacent normal tissues as demonstrated by immunohistochemical staining of 171 breast cancer samples." (PMID 35395857, 2022). "TBK1 inhibition sensitizes breast cancer cells to tamoxifen-induced cell death." (PMID 35395857, 2022). "Interestingly, recent studies showed that FIP200 deletion led to TBK1 activation in mammary tumor and other cells." (PMID 34903812, 2021). "MiR-200c sensitizes breast cancer cells to radiation by targeting TBK1 and EGFR9,10." (PMID 31601781, 2019). "It was reported that TBK1/IKKepsilon inhibitors might improve the treatment of HER2-postive breast cancers together with anti-HER2 therapy." (PMID 25900239, 2015).
breast carcinoma (continued). "Similar to the finding of TBK1 as a potent target for HER2-positive breast cancer, an identification of molecular targets regulated by ERBB3 signal pathways will be beneficial to design a new regime for ERBB3-targeted therapy or a combination therapy for treating colorectal cancers." (PMID 24970817, 2014). "This may explain the positive role of STING/TBK1 in tumor progression of breast cancer." (PMID 39061024, 2024). "Therefore, TBK1 inhibition sensitizes breast cancer cells to tamoxifen-induced cell death." (PMID 39061024, 2024). "Since the enhanced activity of TBK1 (TBK1 K154R) promotes the proliferation of breast cancer cells by targeting the mTOR signaling pathway, it is possible that ubiquitination of TBK1 at different sites may also regulate this proliferation by affecting its activity." (PMID 39061024, 2024). "However, the effects of TBK1 ubiquitination at different sites on the proliferation of breast cancer cells may depend on the E3 ubiquitin ligases which mediate the reaction." (PMID 39061024, 2024). "In the present study, we evaluated mRNA expression patterns of the mitotic kinases Nek2, Mps1/TTK, and TBK1, as well as the expression and association of these proteins with biomarkers of proliferation (Ki67) and EMT (E-cadherin and Vimentin) by using a novel breast cancer TMA." (PMID 36494865, 2022). "Furthermore, treatment of IKBKE‐driven breast cancer cells with a potent inhibitor of TBK1/IKBKE and JAK signaling impaired proliferation and colony formation of TNBC cells, whereas inhibition of JAK alone did not, suggesting that IKBKE regulated tumor cell progression." (PMID 31733040, 2020). "In addition, inflammation in the lung microenvironment may lead to Tank-binding kinase-1 (TBK1)-dependent promotion of proliferation of dormant breast cancer cells." (PMID 31817646, 2019). "By inhibiting RB1CC1, AZI2 accumulates, leading to overactivation of TBK1-IFN, promotion of cytokine expression in breast cancer, CD8T cell infiltration, and improvement of the response of breast cancer to ICI." (PMID 39161768, 2024). "The cell experiments in our study also showed that MARCH1 mediated the TBK1-mTOR signaling pathway to both respond to insulin and EGF stimulation in breast cancer cells." (PMID 39061024, 2024). "It has been reported that autophagy inhibitors promote the expression of pro-inflammatory factors by activating the TBK1-IFN pathway, thereby enhancing the response of breast cancer to immune checkpoint inhibitors (ICIs)." (PMID 39161768, 2024). "We examined the TCGA dataset to understand the differences in the mRNA expression of Nek2, TTK, and TBK1 in NHW (n = 743), NHB (n = 187), and H/L (n = 39) populations with breast cancer based on their self-reported race and ethnicity." (PMID 36494865, 2022). "TBK1 was overexpressed in some basal breast cancer patients (2.3% in TCGA and 2% in METABRIC), and downregulated in other basal breast cancer patients (5.3% in TCGA and 12% in METABRIC)." (PMID 36494865, 2022). "However, we found that loss of FIP200 autophagy function by FIP200-4A mutation did not induce TBK1 activation in mammary tumor cells, suggesting that TBK1 may mediate non-autophagy functions of FIP200 in these cells." (PMID 34903812, 2021). "Although IKKε is not essential for growth of mouse Her2/Neu tumor cells, shRNA-mediated knockdown of TBK1 alone efficiently inhibited growth of both mouse and human HER2-positive breast cancer cells." (PMID 27145266, 2017). "In endocrine-resistant ER+HER2- breast cancer, while hyperactivated AKT1 suppresses cGAS-STING signaling by binding to TBK1 and disrupting the TBK1/STING/IRF3 complex, combining AKT1 inhibitors with STING agonists restores innate immune activation and impairs tumor growth in preclinical models." (PMID 41573551, 2025). "Inhibition of the non-autophagy function of FIP200 allows breast cancer to benefit from immune checkpoint inhibitors, also via activation of the TBK1-IRF pathway." (PMID 39161768, 2024).
breast carcinoma (continued). "Importantly, a deficiency of MARCH1 promotes the migration and the colony formation of breast cancer cells, which can be blocked by H151 (STING inhibitor), GSK8612 (TBK1 inhibitor), or Torin 1 (mTOR inhibitor)." (PMID 39061024, 2024). "Also, in invasive human breast cancer cells MDAMB231, the protein level of STING and phosphorylated TBK1 was higher than in the non-invasive MDAMB453 cells." (PMID 36882786, 2023). "Chemical inhibition of cGAS or TBK1 led to significantly reduced production of the IRF3 target CXCL10 in 66cl4 cells, indicating that the cGAS-STING-TBK1 pathway is important for IFN-I expression in the metastatic mouse breast cancer cells." (PMID 36882786, 2023). "All mitotic regulators analyzed except TBK1 are significantly overexpressed in breast cancers that do not fall under a traditional subtype, or that failed to classify." (PMID 36494865, 2022). "TBK1 and FGFR3 have been used as treatment targets for HER2+ breast cancer." (PMID 33849068, 2021). "Furthermore, Barbie et al27 found that treatment of IKBKE‐driven breast cancer cells with CYT387, a potent inhibitor of TBK1/IKBKE and JAK signaling, reduced the proliferation and migration of TNBC cells, whereas inhibition of JAK alone does not." (PMID 31733040, 2020). "Indeed, breast cancer patients with hypo-phosphorylated ERRα are more likely to respond to hormonal-blockade therapy and have a longer overall survival time than those with hyper-phosphorylated ERRα, which may be a direct consequence of TBK1-mediated ERRα phosphorylation." (PMID 28591144, 2017). "Notably, TBK1 is overexpressed in 26.7% of TCGA breast cancers that do not fall within the molecular classifications, or that failed to classify." (PMID 36494865, 2022). "Additionally, we showed that the redox-regulating compounds triphenylmethane dyes, Gentian Violet and Brilliant Green, and nitroxide Tempol inhibit IKKε, but not TBK1, expression in breast cancer cells." (PMID 28532474, 2017). "The logic of why RKIP has an opposite effect on IFN response in macrophages and breast cancer cells is currently unrecognized, and the effect of RKIP on TBK1 in transformed non-immune cells is presently not known." (PMID 35892864, 2022).